DAAM2 (dishevelled associated activator of morphogenesis 2)
Diseases named in the same sentence as DAAM2 in open-access papers (continued):
Sharing a sentence is not in itself a finding about the gene and the disease.
lung adenocarcinoma (1 paper, 2017). A carcinoma that arises from the lung and is characterized by the presence of malignant glandular epithelial cells. "Analysis of these data revealed that Daam2 expression was positively correlated with HIF1α and pAkt protein expression across this cohort of malignancies, with GBM and lung adenocarcinoma also showing the strongest positive correlation." (PMID 29053101, 2017). "This analysis identified von Hippel Landau (VHL) as one of the proteins from this cohort with the most significant inverse correlation score across this spectrum of malignancies, with lung adenocarcinoma and GBM demonstrating the strongest negative correlations between Daam2 and VHL." (PMID 29053101, 2017).
malignant glioma (1 paper, 2017). A grade III or grade IV glioma arising from the central nervous system. "Here we found that Daam2 promotes tumorigenesis in mouse and human models of malignant glioma." (PMID 29053101, 2017). "To evaluate the role of Daam2 in tumorigenesis, we turned to mouse models of malignant glioma." (PMID 29053101, 2017).
pancreatic adenocarcinoma (1 paper, 2022). "Next, correlations between DAAM2 and immunological characteristics in the tumor microenvironment (TME) of pancreatic adenocarcinoma (PAAD) were evaluated." (PMID 35281277, 2022).
preeclampsia (1 paper, 2021). Preeclampsia is a hypertensive disorder of pregnancy that is characterized by new-onset hypertension with proteinuria presenting after 20 weeks of gestation, and depending on mild or severe forms may initially present with severe headache, visual disturbances, and hyperreflexia. "We also found no change in DAAM2 expression when we sub-analysed the cases by coexistent gestational hypertension or preeclampsia." (PMID 33692394, 2021).
prostate carcinoma (1 paper, 2025). A carcinoma that arises from epithelial cells of the prostate gland. "Consistent with this, structured illumination microscopy in prostate cancer cells revealed signal-dependent nuclear enrichment of myosin VI, which localized in close proximity to AR as well as RNA Pol-II clusters and the actin nucleator DAAM2." (PMID 41443423, 2025).
Sepsis (1 paper, 2023). Sepsis is defined as life-threatening organ dysfunction caused by a dysregulated host response to infection. "Gene entities exhibiting stronger expression in the SIRS-ranked dataset included CFC1, CT62, lnc-DAAM2-1 and lnc-LTBP3-2 and in the sepsis-ranked dataset included TDRD9, DAAM2, OLFM4 and OLAH." (PMID 38332914, 2023). "DAAM2 and OLAH were significantly upregulated in both SIRS (FC>8) and sepsis (FC>20) compared to controls, but approximately 3-fold higher in sepsis, than SIRS." (PMID 38332914, 2023). "Classification of data split into three separate groups: Controls, SIRS and Sepsis achieved an OOB estimate of error rate of 17.99% across all days, revealing three biomarkers of most importance by feature selection i.e., FAM20A, OLAH and DAAM2." (PMID 38332914, 2023).
tumor (7 papers, 2013 to 2023). "In addition, DAAM2 was associated with an inflamed phenotype in the tumor microenvironment (TME)." (PMID 35281277, 2022). "We first performed a pancancer analysis to investigate the immunological role of DAAM2 in all accessible tumor types in the TCGA database." (PMID 35281277, 2022). "Next, we assessed the tumorigenic potential of these GBM cell lines, finding that knockdown of Daam2 resulted in a significant decrease in tumor growth in vivo." (PMID 29053101, 2017). "Both of these lineages are present in one form or another within the bulk tumor, therefore its possible that elevated Daam2 expression is the result of its expression in analogous cell populations that comprise the primary, bulk tumor." (PMID 29053101, 2017). "The correlation of AFF3 and DAAM2 with the candidate miRNAs was detected at all tumor locations." (PMID 37987361, 2023). "Overall, DAAM2 might be a potential biomarker for assessing tumor immunogenicity and guiding immunotherapy." (PMID 35281277, 2022). "In addition, we found that the samples with high DAAM2 expression accounted for a majority of tumor tissues." (PMID 35281277, 2022). "The contribution of the formin family genes to cancer progression and metastasis has recently begun to emerge and here we demonstrate for the first time the ability of FMN2 and DAAM2 to regulate tumour cell migration and invasion, using siRNA-mediated inhibition of each of these formin genes." (PMID 24223803, 2013). "However, it remains to be further clarified whether DAAM2 is merely a biomarker for tumor immunogenicity or has potential regulatory effects on antitumor immunity in PAAD." (PMID 35281277, 2022). "Although DAAM2 is rarely studied in cancer, its significant role in tumor progression is nonnegligible." (PMID 35281277, 2022). "Mice lacking Daam2 demonstrated decreased rates of tumor formation in this model compared to the heterozygote control." (PMID 29053101, 2017). "To directly test this hypothesis, we evaluated expression of VHL and its signaling axis in our Daam2-GOF and Daam2-LOF mouse tumor models." (PMID 29053101, 2017).
cancer (6 papers, 2013 to 2025). A tumor composed of atypical neoplastic, often pleomorphic cells that invade other tissues. "Several Formins (including DAAM1 and DAAM2) are key components of canonical WNT signaling in cancer development, thus they are involved in APC mutation and colon polyp formation." (PMID 37249599, 2023). "Analysis of human cancer data, along with our functional studies in mouse models, strongly suggests that Daam2 expression results in the loss of VHL protein." (PMID 29053101, 2017). "Further experiments found that in several different types of cancer, higher levels of Daam2 are linked with the presence of lower levels of VHL." (PMID 29053101, 2017). "Collectively, these results uncover the potential role of DAAM2 as an immune-related indicator in human cancers, especially PAAD." (PMID 35281277, 2022). "Although the role of DAAM2 in cancers has been preliminarily investigated, its correlations with antitumor immunity are unclear." (PMID 35281277, 2022). "The results suggested a potential role of DAAM2 as an immune-related indicator in human cancers, especially PAAD." (PMID 35281277, 2022). "The findings revealed that DAAM2 showed tight correlations with immunological factors in most cancers, but the highest correlation was found with PAAD." (PMID 35281277, 2022). "In our research, we first analyzed the immunological correlation of DAAM2 across cancers utilizing large-scale RNA-seq data and then validated the expression of DAAM2 in PAAD." (PMID 35281277, 2022). "In the current study, the expression and immunological role of DAAM2 across cancers were first analyzed." (PMID 35281277, 2022). "The results suggested that DAAM2 exhibited positive correlations with a majority of immunomodulators in several cancer types, particularly in gastrointestinal tumors." (PMID 35281277, 2022). "More importantly, deregulation of genes in this module including PLK4, AURKB, DAAM1 and DAAM2 are correlated with aggressive forms of human cancer." (PMID 31142743, 2019). "Together, these studies are the first to define an upstream mechanism regulating VHL suppression in cancer and describe the role of Daam2 in tumorigenesis." (PMID 29053101, 2017). "Together, these studies are the first to define an upstream mechanism regulating VHL protein turnover in cancer and describe the role of Daam2 in tumorigenesis." (PMID 29053101, 2017). "The role of DAAM2 in cancers has been preliminarily summarized." (PMID 35281277, 2022). "Specifically, we found that DAAM2 was positively correlated with the expression of critical immunomodulators, such as CCL5, CXCL9, and CXCL10, as well as the activities of the cancer-immunity cycle." (PMID 35281277, 2022). "We also assessed the correlations between DAAM2 and the expression of immune checkpoints, including TIGIT, CTLA4, CD274, and PDCD1, across cancers." (PMID 35281277, 2022). "To further confirm the role of DAAM2 in mediating cancer immunity in PAAD, we then compared the difference in immunological features of the TME between the High-DAAM2 and Low-DAAM2 subtypes." (PMID 35281277, 2022). "RPPA and bioinformatics approaches revealed that Daam2 expression is inversely correlated with a cohort of genes, including VHL, across a broad spectrum of cancers." (PMID 29053101, 2017). "The nature of this prospective relationship between Daam2 and the existing ubiquitination machinery, and whether these relationships are specific to malignancy or can be extended to development are areas of future investigation and represent potentially new parallels between development and cancer." (PMID 29053101, 2017). "Protein screening and bioinformatics studies revealed that Daam2 and VHL expression is inversely correlated across a broad spectrum of cancers, while functional interrogation of this relationship demonstrated that Daam2 promotes tumorigenesis via suppression of VHL expression." (PMID 29053101, 2017).
cancer (continued). "However, the potential correlation between DAAM2 and immunological features in human cancers has not yet been explored." (PMID 35281277, 2022). "Given that Daam2 expression is inversely correlated with VHL, we next assessed whether Daam2 demonstrates congruent correlation with HIF1α and pAkt in the panel of human cancers." (PMID 29053101, 2017). "Moreover, because Daam2-VHL expression demonstrates a robust, inverse correlation across a spectrum of cancers, this is likely to be a generalized mechanism of VHL suppression in cancer." (PMID 29053101, 2017).
kidney disease (2 papers, 2021 to 2024). "DAAM2, which is expressed by podocytes, colocalizes and associates with INF2, suggesting the existence of crosstalk between the two formins that, given the link between INF2 and renal disease, may explain the renal damage caused by pathogenic DAAM2." (PMID 34685534, 2021). "Among them, Daam2, Pdlim2, Asap1, and Sphk2 all of which have a known relationship to kidney diseases." (PMID 39278930, 2024).
gastrointestinal tumors (1 paper, 2022). "Similarly, DAAM2 expression was highly correlated with most types of TIICs in most gastrointestinal tumors, such as COAD, ESCA, PAAD and READ." (PMID 35281277, 2022).
DAAM2 also shares sentences with these, for which no sentence is quoted: colorectal cancer (2 papers); adenoma (1); cardiomyopathy (1); ciliopathies (1); colon polyp (1); cystic kidney disease (1); demyelination diseases (1); glioblastoma multiforme (1); hearing loss (1); hepatocellular carcinoma (1); injury (1); Intellectual disability (1); melanoma (1); peripheral neuropathy (1); primary ovarian insufficiency (1); Thrombocytopenia (1).